CORO6 (coronin 6)
Synonyms: FLJ14871; ClipinE
Tractability: PROTAC: ubiquitination databases record sites on it.
Gene: Protein-coding gene on chromosome 17 (29,614,756 to 29,622,923, reverse strand). Ensembl gene ENSG00000167549.
Subcellular location (Human Protein Atlas): Golgi apparatus
Gene Ontology:
Molecular function: protein binding; actin filament binding
Biological process: actin filament organization; negative regulation of cellular component organization
Cellular component: actin filament; plasma membrane; lamellipodium
Genetic constraint (gnomAD): Loss-of-function variants: 43 observed, 47.12 expected, observed/expected ratio (o/e) 0.91, 90% interval 0.71 to 1.18. The upper end of that interval is the gene's LOEUF score, 1.18, which puts it in group 5 of 6, group 1 being the genes least tolerant of losing a copy. Missense variants: 650 observed, 656.27 expected, observed/expected ratio (o/e) 0.99, 90% interval 0.93 to 1.06. Synonymous variants: 233 observed, 261.57 expected, observed/expected ratio (o/e) 0.89, 90% interval 0.8 to 0.99.
Homologues: Orthologues: chimpanzee CORO6 (99% identical), macaque CORO6 (99% identical), pig CORO6 (98% identical), guinea pig CORO6 (98% identical), rabbit CORO6 (97% identical), mouse Coro6 (96% identical), rat Coro6 (96% identical), dog CORO6 (87% identical), tropical clawed frog coro6 (78% identical), zebrafish coro6 (71% identical), Drosophila melanogaster coro (56% identical), Caenorhabditis elegans cor-1 (48% identical). Paralogues in human: CORO1B (69% identical), CORO1C (68% identical), CORO1A (64% identical), CORO2B (45% identical), CORO2A (44% identical), CORO7 (33% identical).
Diseases named in the same sentence as CORO6 in open-access papers:
CORO6 is named in the same sentence as 11 diseases in open-access papers, as found by Europe PMC text mining. Sharing a sentence is not in itself a finding about the gene and the disease. The quoted sentences say what the papers report.
hepatocellular carcinoma (3 papers, 2021 to 2025). A malignant tumor that arises from hepatocytes. "Cartilage formation in the liver may cause progressive liver fibrosis, and downregulation of the FXYD6 and CORO6 genes in ALD‐induced mice may result in progression of hepatocellular carcinoma." (PMID 41190282, 2025). "CORO6 and CRIP1 were barely detected in the plasma from colorectal cancer (CRC) and hepatocellular carcinoma (HCC) patients (3.9%, 9 of 229 for CRC and 9.5%, 4 of 42 for HCC), suggesting that these two markers were not hypermethylated in cancers." (PMID 35062960, 2022).
osteosarcoma (2 papers, 2022 to 2023). A usually aggressive malignant bone-forming mesenchymal neoplasm, predominantly affecting adolescents and young adults. "The expression of ubiquitin-related genes (CORO6, UBE2L3, FBXL5, DNAI1, and DCAF8) showed an obvious significance in normal and osteosarcoma tissues." (PMID 36060009, 2022). "The results showed that the mRNA expression level of four ubiquitin-related genes (CORO6, UBE2L3, FBXL5, DNAI1) was significantly increased in osteosarcoma tissues as compared with adjacent normal tissues." (PMID 36060009, 2022). "Likewise, DCAF8 lncRNA-associated mRNA, DCAF8, is a ubiquitin-related gene that decreased in osteosarcoma tissues, and together with other ubiquitin-related genes (CORO6, UBE2L3, FBXL5, DNAI1) seem to play a significant role in the clinical outcome of osteosarcoma." (PMID 36831395, 2023).
renal cell carcinoma (2 papers, 2013 to 2018). "The CORO6 promoter was frequently methylated in renal cell cancer." (PMID 30446011, 2018).
myocardial hypertrophy (1 paper, 2022). "To investigate whether the signal of CORO6 was from cardiomyocytes, we enriched cardiomyocytes from a heart tissue sample obtained from human myocardial hypertrophy (HCM) surgery." (PMID 35062960, 2022).
ovarian serous cystadenocarcinoma (1 paper, 2019). A malignant serous cystic epithelial neoplasm arising from the ovary. "Recently using genome-wide methylation data analysis, five-methylation signature (SLC39A14, PREX2, KCNIP2, CORO6, and EFNB1) were reported as novel independent prognostic biomarker for patients with ovarian serous cystadenocarcinoma, which significantly associated with OS of patients." (PMID 31608277, 2019).
Stroke (1 paper, 2020). Sudden impairment of blood flow to a part of the brain due to occlusion or rupture of an artery to the brain. "Sspo, Shroom3, MuSK, Chrna2, Sorbs2, and Coro6 were upregulated in response to stroke." (PMID 32629989, 2020).
cancer (2 papers, 2021 to 2022). A tumor composed of atypical neoplastic, often pleomorphic cells that invade other tissues. "Moreover, the expression level of CORO6 was also highly associated with grade (G), stage, and pathological tumor/node/metastasis (TNM Classification of Malignant Tumors; Union for International Cancer Control) stage in ccRCC patients (top)." (PMID 34026752, 2021). "Similar to other coronin members, one early report suggested that CORO6 was over-induced in breast cancer, suggesting that it may also play an oncogenic role in cancer development." (PMID 34026752, 2021). "Therefore, disruption in the CORO6 level may prevent the formation of protrusive structures and subsequently impair the invading capacity of cancer cells." (PMID 34026752, 2021). "Of note, our data illustrated that IWP-O1 had no ability to affect the expression level of CORO6 at both the mRNA and protein levels, suggesting that the anti-cancer effect of IWP-O1 was due to WNT inhibition but not the indirect effect from CORO6 reduction." (PMID 34026752, 2021).
tumor (2 papers, 2021). "The CORO6 expression level was highly associated with tumor stage, tumor grade, tumor metastasis, and overall survival." (PMID 34026752, 2021). "Importantly, the CORO6 level was tightly associated with tumor metastasis and OS of ccRCC patients, strengthening the prognostic value of CORO6 in ccRCC patients." (PMID 34026752, 2021). "The IHC results consistently supported the potential tumor-promoting role of CORO6 in ccRCC development, showing CORO6 was significantly upregulated in ccRCC tumors using the adjacent kidney tissues as controls." (PMID 34026752, 2021). "We detected that CORO6 protein was significantly higher expressed in tumor tissues compared with adjacent normal tissues." (PMID 35003366, 2021). "Taken together, all of these data suggest that the CORO6 level is significantly upregulated in ccRCC patients and is further increased as the tumor progresses to the lethal stage." (PMID 34026752, 2021). "Together, our data define the tumor-promoting role of CORO6 in ccRCC progression and provide a compelling rationale to develop CORO6-targeted therapies for improved treatment of ccRCC patients." (PMID 34026752, 2021). "Here, we investigated CORO6 as a tumor-promoting factor in ccRCC development." (PMID 34026752, 2021). "Furthermore, a second xenograft mouse model validated that CORO6 significantly promoted ccRCC tumor growth attenuated by WNT signaling inhibitor IWP-O1, suggesting the involvement of WNT signaling in CORO6-mediated ccRCC growth in vivo." (PMID 34026752, 2021). "Importantly, CORO6 expression level was an independent predictor of tumor metastasis and overall survival in RCC patients." (PMID 34026752, 2021). "Moreover, paired comparison indicated that CORO6 protein was more expressed in tumor tissue than that in adjacent normal tissues most of the paired HCC patients." (PMID 35003366, 2021). "Analysis from both The Cancer Genome Atlas Kidney Renal Clear Cell Carcinoma dataset and our RCC samples demonstrated that the expression level of CORO6 was significantly higher in RCC patients than in normal kidney tissues, and its level was highly associated with tumor stage and grade." (PMID 34026752, 2021). "Interestingly, upregulation of CORO6 was observed in tumor (T) stages III and IV compared to T stages I and II (top)." (PMID 34026752, 2021). "In vivo experiments suggest that knockdown of CORO6 inhibited the tumor growth." (PMID 35003366, 2021). "Importantly, the in vivo data also confirmed that CORO6 depletion suppressed RCC tumor growth." (PMID 34026752, 2021). "Furthermore, we prove that CORO6 knockdown attenuates HCC tumor growth in mice." (PMID 35003366, 2021). "Moreover, the in vivo data suggested that CORO6 knockdown indeed suppressed RCC tumor growth." (PMID 34026752, 2021). "Consistent with our in vitro findings, CORO6 depletion by two independent shRNAs led to a significant suppression of ccRCC tumor growth monitored by tumor size, growth curve, and tumor weight, suggesting that CORO6 indeed acted as a tumor-promoting factor in the development of ccRCC." (PMID 34026752, 2021). "To further investigated if CORO6 protein was dysregulated in HCC, we proceeded by performing immunohistochemistry (IHC) staining in adjacent normal tissues (ANT) and HCC tumor tissues." (PMID 35003366, 2021). "All these data suggest that CORO6 is highly expressed in RCC cell lines and ccRCC patients and may serve as a tumor-promoting factor in determining ccRCC progression." (PMID 34026752, 2021). "Collectively, our results uncover a novel function of CORO6 in HCC progression and prove that the activation of WNT signaling is responsible for the tumor-promoting role of CORO6, which may offer a new target for therapeutic gain of treating HCC." (PMID 35003366, 2021).
CORO6 also shares sentences with these, for which no sentence is quoted: Clear Cell Renal Cell Carcinoma (1 paper); colorectal cancer (1); liver fibrosis (1).